NOTCH1 (notch receptor 1)
Diseases named in the same sentence as NOTCH1 in open-access papers (continued):
Sharing a sentence is not in itself a finding about the gene and the disease.
tumor (continued). "Loss of Notch2 in CD8+ T cells (but not of Notch1), has been shown to promote tumor growth in mice; and blockade of nuclear translocation of Notch2 intracellular domain (NIC), the active form of Notch, inhibits the cytotoxic efficacy of CD8+ T cells on hepatocellular carcinoma." (PMID 39491031, 2024). "Moreover, NF-κβ1 activation has strengthened the activation of the Notch1 pathway, and once NF-κβ1 and Notch1 are activated, they inhibit the expression of peroxisome proliferator-activated receptor-γ (PPARγ), and therefore, they enhance tumor proliferation." (PMID 38817387, 2024). "However, since the NOTCH1 mutation has been found with high frequency in HNSCC and is nevertheless rare in cancers other than SCC, the pathogenesis must be different influenced by the tumor context in which it develops." (PMID 37008245, 2023). "However, RA switches the effect of the Notch1 pathway to tumor suppression." (PMID 36879115, 2023). "All these results suggest that the NOTCH1 pathway may have dual function in this tumor type." (PMID 37859809, 2023). "However, low doses of IFN-γ produced at the tumor site by host-infiltrating cells or during immunotherapy can enhance tumor cell survival, induce risk of metastasis and expression of EMT transcription factors via activation of ICAM1-PI3K-Akt-Notch1 signaling in cancer cells." (PMID 36835413, 2023). "Our findings, suggest that the Cbl-b-Notch1 axis could represent a new functional immune-checkpoint that dampens T-cell responses in the tumor microenvironment and that blockade of this pathway may be a key strategy to overcome tumor-induced immunosuppression." (PMID 36090975, 2022). "Furthermore, NGS of the tumor tissue of the same patients identified tumor-specific pathogenic or likely pathogenic mutations in Kelch-like ECH-associated protein 1 (KEAP1), neurogenic locus notch homolog protein 1 (NOTCH1), and KRAS only in responders." (PMID 36844924, 2022). "In aggressive NOTCH1-mutated human PDX-T-ALL models, the l-asparaginase-containing VXL regimen, in combination with IACS-010759, led to the metabolic and transcriptional collapse of T-ALL cells resulting in a significant reduction in tumor burden and prolonged survival." (PMID 35589701, 2022). "Until now, the effects of NOTCH1 on tumor immune microenvironment in ESCC remain largely unknown." (PMID 36119057, 2022). "Furthermore, tumor grade and NOTCH-1 have shown to be positively correlated." (PMID 36476410, 2022). "The decrease in APOE expression may promote tumor metastasis through NOTCH1, HIF1A, and TGFB1." (PMID 36428687, 2022). "Besides, Notch1 inhibition improves tumor responses to immune checkpoint inhibitors." (PMID 36119081, 2022). "Several reports have suggested that Trop2 expression regulates tumor cell resistance to therapeutic drugs, including tamoxifen and trastuzumab, among others, which could be explained by its effect regulating the Notch1 signaling pathway in some cells." (PMID 35625820, 2022). "In addition to tumor activation, NOTCH1 also promotes the immune response depending on Tregs." (PMID 35332121, 2022). "Vascular cell adhesion molecule 1 (VCAM1) induction in endothelial cells can regulate tumor progression, provide angiogenic factors, promote neutrophil infiltration and tumor cell adhesion to the endothelium, and promote metastasis by sustaining vascular Notch1 signaling." (PMID 35464435, 2022).
tumor (continued). "Therefore, we asked if genetic KO or pharmacological inhibition of Cbl-b could be a strategy to enhance T-cell functions and counteract tumor-induced immunosuppression by promoting Notch1." (PMID 36090975, 2022). "However, additional studies suggested that while the tumor-suppressor role may reside with Notch 1, Notch 2 acts more like an oncogene, and therefore, targeting Notch 2 may have merit." (PMID 34059639, 2021). "Importantly, Western blotting analysis on tumour samples also revealed that depletion of circNOTCH1 could block GPER‐induced NOTCH1 expression." (PMID 33237585, 2021). "However, early characterization of the genomics landscape found that inactivating mutations of NOTCH1 frequently occur in HNSCC, suggesting that NOTCH1 may also function as a tumor suppressor." (PMID 34336664, 2021). "Therefore, inhibition of HER2 followed by inhibition of JAG1 or NOTCH1 may be more effective in preventing drug resistance and tumor progression than a simultaneous blockade." (PMID 34374886, 2021). "Moreover, Notch 1 expression in primary tumor biopsy could indicate a poor response to this treatment in mCRC patients." (PMID 33916610, 2021). "However, both the oncogenic and tumor-suppressive roles of Notch1 have been reported in LUSC54,55." (PMID 33976158, 2021). "However, CD34 MVD in Notch 1 hot spots may be a new prognostic factor with different means from CD34 MVD measured in the entire tumor tissue." (PMID 34642389, 2021). "Thus, to experimentally test the relationship between Notch signaling, NE differentiation and intrinsic tumor immunity, we overexpressed the intracellular, transcriptionally active domain of NOTCH1 (N1ICD) in a NE human SCLC cell line (NCI-H82), which grows in suspension in cell culture." (PMID 34162872, 2021). "To figure out the mechanism underlying the tumor-suppressive effect of FTO expression on BCa cells, we detected the expressions of the known differentially m6A methylated genes, including MALAT1, CSNK2A2, ITGA6, and NOTCH1, which were found to correlate with BCa progression in previous studies." (PMID 34499008, 2021). "In addition, blocking the DLL4/Notch1 interaction in cancer is being explored in clinical trials because DLL4 inhibition has been shown to cause non-productive vessel formation within the TME, thereby inhibiting tumor growth." (PMID 33681228, 2021). "Thus, our results are consistent with the notion that elevated Notch1 signaling drives tumor cell differentiation towards the luminal fate, whereas decreased Notch1 signaling or elevated Wnt signaling promotes tumor differentiation towards a more basal, skin, or pluripotent fate." (PMID 34475389, 2021). "Previous studies have reported the overexpression of Notch components including DLL1, Notch1 and ASCL1 correlates with a higher grade of glioma and a worse prognosis, indicating an activated Notch signaling is usually associated with more aggressive tumor phenotype." (PMID 33176854, 2020). "However, the Patient 1 tumor and its derivative cells lines did not harbor NOTCH1 mutations, suggesting this is not a universal feature required for metastases." (PMID 33333825, 2020).
tumor (continued). "However, other groups have reported data suggesting that NOTCH1 has oncogenic properties in a subset of HNSCC cases, leading to the hypothesis that the NOTCH1 pathway may have dual function in this tumor type." (PMID 33322834, 2020). "Previously, we reported that stimulation of the NOTCH pathway in NOTCH1-wt HNSCC cell lines led to significant downregulation of two prominent proto-oncogenes, AXL and CTNNAL1 (α-catulin), which have both been linked to aggressive biologic and clinical features in HNSCC and other tumor types." (PMID 33322834, 2020). "We recently reported that HNSCC cell lines harboring NOTCH1 loss of function (LOF) mutations are highly dependent on phosphatidylinositol 3-kinase (PI3K) signaling and that treatment with drugs blocking this pathway leads to tumor cell death in this genomic subtype." (PMID 33322834, 2020). "Moreover, in‐depth mechanistic research showed that BRD4 was concentrated at the promoter region of Notch1 and may be involved in the process of tumor metabolism." (PMID 33135348, 2020). "Thus Notch1 acts as a tumor suppressor in the skin epithelium." (PMID 32796631, 2020). "Expression pattern analysis of the NOTCH1 gene indicated that TNBC and basal-type tumours exhibited significantly increased levels of NOTCH1, regardless of whether BRCA1 was mutated." (PMID 32591500, 2020). "Furthermore, we elucidated the action mechanisms of ETS1 as a tumor suppressor not only by directly activating down-stream targets linked with tumor cell proliferation/growth but also trans-activation of other tumor suppressor genes, such as ADAMTS9, TXNIP, STAT5A, and NOTCH1." (PMID 32477936, 2020). "BRD4 was enriched at Notch1 promoter region and may be involved in the process of tumor metabolism." (PMID 33135348, 2020). "The expression of NOTCH1, a disintegrin and metalloproteinase 12 (ADAM-12), hypoxia-inducible factor 1 alpha (HIF-1α), and heparin-binding epidermal growth factor (HB-EGF) under hypoxic conditions has been implicated in invadopodia formation, tumour invasiveness, and metastasis." (PMID 32386517, 2020). "Therefore, by hyperactivating Notch-1 in the vessels, ponatinib exerts an “on-target off tumor effect”, which leads to deleterious effects and may explain the drug’s vasculotoxicity." (PMID 32197359, 2020). "Additionally, high levels of Notch1 may be induced in NSCLC CSCs by specific environmental conditions, such as tumor associated hypoxia." (PMID 30873026, 2019). "However, tumor growth was reversed in group with NOTCH1 overexpression cells (P<0.05)." (PMID 31031809, 2019). "Additionally, the recent finding of a higher frequency of NOTCH1 mutations in aged oesophageal mucosa compared to tumours, raises the possibility that NOTCH1 mutations do not play a significant role in HNSCC40." (PMID 31427592, 2019). "Therefore, it can be suggested that PTC patients with higher Notch1 signaling activity may tend to have more tumor invasiveness and can benefit from more active treatment (such as RRA)." (PMID 30622441, 2019). "Interestingly, the ability of ΔNp63 to affect NOTCH1 expression negatively has also been observed in the epidermis of ΔNp63 knock‐out mouse embryos, suggesting that the ΔNp63/NOTCH1 pathway might be indicative of a regenerative state of tumour cells." (PMID 30845357, 2019). "Moreover, Notch1 signaling shows significant variability in tumor status across different tissue types, which may promote or inhibit tumor progression." (PMID 31739580, 2019). "In addition, it has been observed that NOTCH1 could suppress tumor proliferation under normoxia, while under hypoxia, NOTCH1 is involved in the promotion of tumor." (PMID 31217907, 2019).
tumor (continued). "Moreover, our findings indicated that when tumor cells interacted with stromal cells in the presence of pro-inflammatory stimuli, TNFα-induced p65 activation has led to elevated Notch1 expression and activation, which then gave rise to elevated production of CXCL8." (PMID 31105691, 2019). "Moreover, Notch1 is more expressed in peritumor-tissue GSCs compared to tumor-core GSCs." (PMID 30832246, 2019). "The fact that Notch1+ tumour cells present an expression profile very similar to the signature of Notch1+ ISCs, prompts us to speculate that Notch1+ tumour cells might derive from +4 ISCs, shown to express lower levels of Lgr5 than CBCs and paramount for intestinal regeneration." (PMID 30696875, 2019). "In these models, we found that Notch1+ tumour cells strikingly resemble wild-type ISCs, inferring that they might represent normal stem cells that were engulfed during tumour growth and thrive in the tumour environment thanks to paracrine mitogenic signals from surrounding cells." (PMID 30696875, 2019). "Therefore, NOTCH1 may have a dual function in cancer, acting either as an oncogene in several leukemia cases or as a tumor suppressor gene in HNSCCs." (PMID 31191362, 2019). "The prevalence of loss-of-function mutations of NOTCH1 in HNSCC has led to the hypothesis that this protein acts as a tumor suppressor rather than as an oncogene in this type of tumor." (PMID 31861809, 2019). "FBW7 depletion in BM-derived stromal cells (BMSCs) results in the accumulation of Notch-1 intracellular domain (NICD1) and increased secretion of CCL2, which in turn promotes recruitment of monocytic myeloid-derived suppressor cells (Mo-MDSCs) and tumor-associated macrophages (TAMs)." (PMID 30053872, 2018). "In addition, we assessed the correlation between Notch1 expression and clinicopathologic characteristics in 33 patients and found that Notch1 expression was positively correlated with tumour grade and negatively correlated with Karnofsky Performance status (KPS) score (P < 0.05)." (PMID 30170559, 2018). "Speculatively, treatment with HDAC6i might exert stronger therapeutic effects in tumor cells bearing Notch3 mutations in the absence of Notch1 mutations, such as the TALL1 cell line." (PMID 29643474, 2018). "Finally, loss of Notch1 in tumor cells did not affect the protein expression of Notch2, Jag1, and BEC marker Sox9 as well as mRNA levels of Notch targets, including Hes5 and Hey2." (PMID 29545603, 2018). "Therefore, we speculated that reduction of Treg cells and MDSCs in tumor sites was a possible consequence of the down-regulation of tumor-derived TGF-β1 induced by Notch1 knockdown." (PMID 29301578, 2018). "However, our data suggested that Notch4 might function as a tumor suppressor in lung SCC and as a tumor activator in lung ADC similar with Notch1." (PMID 30034624, 2018). "Interestingly, Notch-1 may act as an oncogene or a tumor suppressor gene even within the same tumor type, and recently, it has been implicated in induction of cellular senescence mediated by p16 and p21." (PMID 29618945, 2018). "Indeed, different Notch family members may have tumor supporting and tumor suppressing roles, such as Notch1 and Notch2, respectively." (PMID 29383147, 2017). "Importantly, Notch1 and NFκB could independently contribute to tumor progression, but their interaction is thought to be a determinant that would affect the clinical outcome of the disease and therapeutic intervention." (PMID 29104587, 2017). "Moreover, Notch1 and Notch2 protein levels are decreased in the tumor." (PMID 29206870, 2017). "This patient's tumor demonstrated 8 mutations overall including alterations in the PI3K, MAPK pathways (mutations in FBXW7, FGFR1) with concurrent epigenetic and transcriptional deregulation, specifically ARID1A, ETV1 rearrangement, NOTCH1 APIP-NOTCH1 fusion, and MYST3 amplification." (PMID 28781987, 2017).
tumor (continued). "Importantly, the level of NICD was significantly higher in P. gingivalis–infected tumor xenografts compared with uninfected controls (5 out of 6 pairs), suggesting that the P. gingivalis–induced activation of Notch1 was responsible for the development of chemoresistance in vivo." (PMID 28388583, 2017). "In addition, overexpression of Notch1 had tumor suppressive effects in MTC." (PMID 28122586, 2017). "Besides TGFβ, hypoxia and inflammation may activate Notch1 to promote EMT in the tumor microenvironment via transcriptional factors such as HIF1α17 and NF-κB53, respectively." (PMID 29170450, 2017). "Notably, the observed inhibitory effects of anti-TGFβ antibody upon tumor progression in mice may involve TGFβ downstream effectors other than Notch1, representing a limitation of the current study." (PMID 29170450, 2017). "Interestingly, even though Notch1 expression levels were in average decreased in tumor samples when compared to normal ones, including LCM samples, some PCa samples showed low levels, while others unchanged or increased levels when compared to normal prostate tissues." (PMID 27384993, 2016). "Therefore, it indicated that NOTCH1 blockade could decrease tumor growth through target CSC phenotype in HNSCC xenograft mouse model." (PMID 27108536, 2016). "Furthermore, although molecular links between Notch1 and NF-κB during tumor progression and metastasis have been suggested by the previous work, a mechanism of disrupting or directly regulating Notch1 signaling from within the NF-kB/Snail/YY1/RKIP loop was unclear." (PMID 26716415, 2016). "Notch1's tumor suppressor role in CSCC may involve beta‐catenin/Wnt pathway." (PMID 27228302, 2016). "Therefore, we hypothesized that Notch1 and MenaINV are both required for the formation of the invadopodia necessary for tumor cells to undergo transendothelial migration." (PMID 27901093, 2016). "Therefore, it would be reasonable to hypothesize that Notch1 signaling inhibition may favor anti-tumor immune and it might provide a new target for immunotherapy of ovarian epithelial carcinoma." (PMID 27259477, 2016). "The tumor inhibition rate was evaluated, followed by the quantification of messenger ribonucleic acid (mRNA) and protein expression of notch signaling components NOTCH-1, NOTCH-3, NOTCH-4, JAG-1, DLL-4, Hes-1, and Hey-1 using quantitative polymerase chain reaction (qPCR)." (PMID 26762567, 2016). "However, there was a paper reported anti-tumor role of NOTCH1 in GC." (PMID 27938406, 2016). "Therefore, combinational NOTCH1 inhibition by DAPT may significantly reduce tumor growth by reducing CSC population in HNSCC in vitro and in vivo." (PMID 27108536, 2016). "A limited number of studies suggest that NOTCH1 may act as a tumor suppressor in SCLC." (PMID 26491213, 2015). "Furthermore, in accordance with the heterogeneity of SNAI2 expression in the primary PCa, the strength of the staining of both SOX2 and NOTCH1 was frequently distinct or strong in the tumor cell clusters forming the expansion/invasion front of high-grade PCa foci." (PMID 25686823, 2015). "Besides having a pivotal role for the success of an experimental therapeutic application of TRAIL or DR5 agonists, inhibition of Notch1 signaling might also be interesting with regard to an efficient TRAIL-mediated immunologic tumor defense." (PMID 26469969, 2015).